HUPCOS (hormone disturbance in PCOS associated regulator of RBPMS)
Synonyms: lnc-ZSCAN2-5:15
Gene: Long non-coding RNA gene on chromosome 15 (84,631,440 to 84,660,091, forward strand). Ensembl gene ENSG00000291159.
Gene Ontology:
Biological process: SRP-dependent cotranslational protein targeting to membrane, signal sequence recognition
Cellular component: signal recognition particle, endoplasmic reticulum targeting